PRMT5 (protein arginine methyltransferase 5)
Diseases named in the same sentence as PRMT5 in open-access papers (continued):
Sharing a sentence is not in itself a finding about the gene and the disease.
oropharyngeal squamous cell carcinoma (2 papers, 2017 to 2018). "Nuclear PRMT5/p16-negative tumors were associated with poor prognosis in oropharyngeal squamous cell carcinoma when compared to nuclear PRMT5-negative/p16- positive tumors." (PMID 29568320, 2018). "In this study, we examined expression profile of PRMT5 at subcellular levels in oropharyngeal squamous cell carcinoma (OPSCC) and assessed its correlation with disease progression and patient outcome." (PMID 28107179, 2017). "In this study, we examined the PRMT5 subcellular expression pattern in surgically treated oropharyngeal squamous cell carcinoma (OPSCC) samples and correlated that with survival, p16 status, and other clinical and pathological variables." (PMID 28107179, 2017).
pulmonary arterial hypertension (2 papers, 2022 to 2024). Pulmonary arterial hypertension (PAH) is a group of diseases characterized by mean pulmonary artery pressure >20 mmHg and elevated pulmonary arterial resistance leading to right heart failure. "These experiments suggested that PRMT5 may be a therapeutic target in CRC treatment, as tadalafil is already been approved by FDA for erectile dysfunction and pulmonary arterial hypertension (PAH) treatment." (PMID 36474242, 2022).
renal carcinoma (2 papers, 2023 to 2025). A carcinoma arising from the epithelium of the renal parenchyma or the renal pelvis. "Furthermore, elevated PRMT5 levels were associated with unfavorable clinical outcomes in patients with renal cancer." (PMID 40756764, 2025). "The clinical association between PRMT5 expression, meR549-ACSL4 levels, and poor prognosis underscores the translational potential of targeting PRMT5 in renal cancer therapy." (PMID 40756764, 2025). "We conducted a mass spectrometry (MS) analysis of PRMT5-binding proteins to explore the molecular pathway through which PRMT5 suppresses ferroptosis in renal cancer cells." (PMID 40756764, 2025). "While our study strongly supports the role of PRMT5 in regulating ferroptosis in renal cancer, several areas warrant further investigation." (PMID 40756764, 2025). "Thereafter, IHC staining of PRMT5 protein in renal cancers from the HPA database and proteomic data from the FUSCC cohort including 232 ccRCC patients confirmed the low-expression of PRMT5 in ccRCC at the protein level." (PMID 37781030, 2023). "However, it is still not fully understood how PRMT5 influences the progression of renal cancer, particularly its potential involvement in the ferroptosis of renal cancer cells." (PMID 40756764, 2025). "The role of PRMT5 in the process of ferroptosis was further examined in 786-O and ACHN renal cancer cell lines." (PMID 40756764, 2025). "We first explored the IHC staining of PRMT5 protein from the HPA database, which confirmed that PRMT5 was down-regulated in renal cancers at the protein level." (PMID 37781030, 2023). "Additionally, we show that PRMT5 promotes the binding of ACSL4 to UBR5 via arginine 549 (R549) methylation, thereby inhibiting ferroptosis in renal cancer cells." (PMID 40756764, 2025).
rhabdomyosarcoma (2 papers, 2021 to 2022). A rare aggressive malignant mesenchymal neoplasm arising from skeletal muscle. "The expression of PRMT1, CARM1, PRMT5, PRMT7, PRMT8 and PRMT9 were all elevated in rhabdomyosarcoma, CARM1 and its direct interaction with histone acetyltransferase PCAF jointly were also detected to exert an increased expression of myogenin gene and lead to rhabdomyosarcoma cell differentiation." (PMID 35311114, 2022).
steatosis (2 papers, 2020 to 2022). Increased lipid within the cytoplasm of cells. "Furthermore, H&E and Oil Red O staining of liver sections from liver-specific Prmt5 KO mice also showed reduced pathology associated with steatosis, hepatocyte bubble morphology, and inflammation in livers." (PMID 36499164, 2022).
systemic sclerosis (2 papers, 2024 to 2025). A chronic disorder, possibly autoimmune, marked by excessive production of collagen which results in hardening and thickening of body tissues. "Recently, anti-protein arginine methyltransferase 5 (PRMT5) antibodies has been identified a novel marker for systemic sclerosis (SSc)." (PMID 40790333, 2025).
AIDS (1 paper, 2020). A syndrome resulting from the acquired deficiency of cellular immunity caused by the human immunodeficiency virus (HIV). "In addition, further study is needed into how the expression levels of PRMT5 and PRMT7 contribute to the progression of a patient from HIV-1 infection to development of AIDS." (PMID 32210193, 2020).
alcoholic fatty liver disease (1 paper, 2023). Lipid infiltration of the hepatic parenchymal cells that is due to alcohol abuse. "Severe side effects in liver, i.e. development of non‐alcoholic fatty liver disease, should thus be taken into account upon chronic treatment with this PRMT5 inhibitor." (PMID 36946061, 2023).
amebiasis (1 paper, 2024). A parasitic infectious disorder caused by amoebas. "The results of this study suggest that PRMT5 is a potential target for the development of new therapeutic strategies against the spread of amebiasis." (PMID 39795118, 2024). "Therefore, our results suggest that PRMT5 could be considered a potential target for the development of novel therapeutic strategies against amebiasis." (PMID 39795118, 2024).
asthma (1 paper, 2024). "These pathways including, graft versus host disease, allograft rejection, asthma, mismatch repair, aminoacyl tRNA biosynthesis, and DNA replication were activated in the high PRMT5 group." (PMID 39678513, 2024).
Azoospermia (1 paper, 2022). Absence of any measurable level of sperm,whereby spermatozoa cannot be observed even after centrifugation of the semen pellet. "Although the precise underlying mechanisms warrant further investigation, diminished CT47 expression in patient testes may dampen the functional response to testosterone involving nuclear-to-cytoplasmic translocation of PRMT5 for the initiation of spermatogenesis in adults, resulting in azoospermia." (PMID 35918318, 2022).
benign ovarian tumors (1 paper, 2013). "Similar to our study, low levels of PRMT5 have been reported at low frequency in normal ovarian tissues and benign ovarian tumors." (PMID 24326178, 2013).
bone tumors (1 paper, 2025). "Collectively, evidence highlights PRMT5 inhibitors as promising therapeutic targets for bone tumors, particularly in tumor subtypes exhibiting high dependency on PRMT5 and harboring specific splicing factor mutations." (PMID 41268214, 2025).
Burkitt lymphoma (1 paper, 2022). A rare form of malignant mature B-cell non-Hodgkin lymphoma. "HNRNPH1, as a member of the hnRNP family, is associated with the methyltransferase function of PRMT5 and is involved in the tumorigenic progression of Burkitt lymphoma and HCC." (PMID 36499164, 2022).
cardiomyopathy (1 paper, 2025). A disease of the heart muscle or myocardium proper. "This discovery could pave the way for identifying novel therapeutic targets for cardiomyopathy associated with PRMT5 deficiency." (PMID 40076920, 2025).
cerebral infarction (1 paper, 2024). An ischemic condition of the brain, producing a persistent focal neurological deficit in the area of distribution of the cerebral arteries. "We found that PRMT5-target genes in OGD are highly enriched for those that were downregulated after cerebral infarction in the MCAO mouse, suggesting that our model may apply in animals." (PMID 38372724, 2024).
Cerebral ischemia (1 paper, 2024). Restriction of arterial blood supply to the brain associated with insufficient oxygenation to support the metabolic requirements of the tissue. "Together, these findings revealed a novel epigenetic mechanism of PRMT5 in cerebral ischemia and uncovered a potential target for neuroprotection." (PMID 38372724, 2024).
Cervical lymphadenopathy (1 paper, 2023). Enlarged lymph nodes in the neck. "With aging, key clinical characteristics of Eμ-PRMT5/TCL1 mice at ERC included pronounced cervical lymphadenopathy and palpable splenomegaly." (PMID 36609611, 2023).
cervical tumor (1 paper, 2021). "The result showed that cervical tumor tissues expressed higher levels of PRMT5 compared to normal tissues." (PMID 34522232, 2021).
chronic myelomonocytic leukemia (1 paper, 2025). A myelodysplastic/myeloproliferative neoplasm which is characterized by persistent monocytosis, absence of a Philadelphia chromosome and BCR/ABL fusion gene, fewer than 20 percent blasts in the bone marrow and blood, myelodysplasia, and absence of PDGFRA or PDGFRB rearrangement. "Mechanistically, in diseases harboring AS factor mutations (such as MDS and chronic myelomonocytic leukemia), tumor cells become dependent on PRMT5 to maintain a “barely stable” splicing system; thus, PRMT5 inhibition induces synthetic lethality, selectively triggering tumor cell death." (PMID 41268214, 2025).
diabetes (1 paper, 2021). "Beyond cancer, evidence suggests that PRMT5 plays an important role in diabetes." (PMID 34685445, 2021). "Notably, emerging studies have demonstrated the pathological contribution of PRMT5 in the progression of inflammatory diseases, such as diabetes, cardiovascular diseases, and neurodegenerative disorders." (PMID 34685445, 2021). "Thus, further studies are required to understand the nuanced role of PRMT5 in T2DM models, to aid better exploration of PRMT5 as a viable therapeutic target in diabetes." (PMID 34685445, 2021).
diabetic nephropathy (1 paper, 2022). "Since several PRMT5 inhibitors are under preclinical and clinical studies for the treatment of cancer, our results suggest that PRMT5 inhibitors may have other therapeutic implications in human diseases, such as diabetic retinopathy, macular degeneration, and diabetic nephropathy." (PMID 35531958, 2022).
diabetic retinopathy (1 paper, 2022). "Our results provide compelling evidence demonstrating a crucial role of PRMT5 in hypoxia-induced angiogenesis and suggest that inhibition of PRMT5 may provide novel therapeutic strategies for the treatment of abnormal angiogenesis-related diseases, such as cancer and diabetic retinopathy." (PMID 35531958, 2022).
Duchenne muscular dystrophy (1 paper, 2015). Duchenne muscular dystrophy (DMD) is a neuromuscular disease characterized by rapidly progressive muscle weakness and wasting due to degeneration of skeletal, smooth and cardiac muscle. "Our study revealed that inactivation of Prmt5 in MuSC of mdx mice resulted in a severe loss of muscle volume and recapitulated several symptoms of human Duchenne muscular dystrophy within 90 days." (PMID 26028225, 2015).
ductal carcinoma (1 paper, 2021). "A more recent study indicated that PRMT5 levels are up‐regulated in MCF‐7, MDA‐MB‐231 and MCF‐10A cell lines as well as in clinical samples of ductal carcinoma." (PMID 33462997, 2021).
EBV infection (1 paper, 2021). "PRMT5 has been shown to be overexpressed in a wide variety of cancers and other diseases, and is involved in the regulation of Epstein-Barr virus infection, viral carcinogenesis, spliceosome, hepatitis B, cell cycles, and various signaling pathways." (PMID 34513846, 2021). "PRMT5 overexpression may be an important mechanism to promote the immortalization of B cells after EBV infection." (PMID 34513846, 2021).
embryonal carcinoma (1 paper, 2008). A non-seminomatous malignant germ cell tumor characterized by the presence of large germ cells with abundant cytoplasm resembling epithelial cells, geographic necrosis, high mitotic activity, and pseudoglandular and pseudopapillary structures formation. "In contrast, PRMT5 was moderately higher in IGCNU (p = 0.033), while embryonal carcinoma (p = 0,091) and seminoma (p = 0,091) express a similar level of PRMT5 compared to normal testicular tissue." (PMID 18992153, 2008). "In embryonal carcinoma, expression of BLIMP1 and PRMT5 was weak and cytoplasmatic." (PMID 18992153, 2008). "Moreover, BLIMP1/PRMT5 and histone H2A and H4 arginine 3 dimethylation was present in IGCNU and most seminomas, while downregulated in embryonal carcinoma (EC) and other nonseminomatous tumors." (PMID 18992153, 2008).
endocrine tumor (1 paper, 2025). "Such a mechanism may provide an additional layer of regulatory control over PRMT5-dependent signaling in endocrine tumor contexts, linking upstream kinase activity to chromatin-associated transcriptional programs." (PMID 40919714, 2025).
endometrial carcinoma (1 paper, 2016). A malignant tumor arising from the epithelium that lines the cavity of the uterine body. "In another study, it has been reported that UHRF1 associates with PRMT5 (Protein arginine N-methyltransferase 5) in endometrial carcinoma." (PMID 27839516, 2016).
esophageal adenocarcinoma (1 paper, 2020). A malignant tumor with glandular differentiation arising predominantly from Barrett mucosa in the lower third of the esophagus. "Consistent with the findings that overexpression of TXNIP promotes DNA damage in esophageal adenocarcinoma, senescence in vascular endothelial cells, we demonstrated that TXNIP, may function downstream of PRMT5 to regulate DNA damage signaling and p21-mediated cellular senescence in U2 OS cells." (PMID 32023548, 2020).
Ewing sarcoma (1 paper, 2025). A small round cell tumor that lacks morphologic, immunohistochemical, and electron microscopic evidence of neuroectodermal differentiation. "Immunoblotting across a panel of Ewing sarcoma cell lines detected PRMT1 and PRMT5 expression and associated activity." (PMID 40823091, 2025). "In this study, we identify a role for the arginine methyltransferases PRMT1 and PRMT5 in the survival of Ewing sarcoma cells." (PMID 40823091, 2025).
fibrosis (1 paper, 2024). the formation of excess fibrous connective tissue in an organ or tissue in a reparative or reactive process. "As cardiac fibrosis is regulated by various factors, including fibroblast proliferation, further mechanistic studies are needed to analyze the fibrosis-related functions of PRMT5." (PMID 38503742, 2024).
germ cell tumor (1 paper, 2008). A benign or malignant, gonadal or extragonadal neoplasm that originates from germ cells. "In the present study, we investigated the expression of BLIMP1/PRMT5 during human fetal germ cell development and in testicular germ cell tumors." (PMID 18992153, 2008).
Glucose intolerance (1 paper, 2020). Glucose intolerance (GI) can be defined as dysglycemia that comprises both prediabetes and diabetes. "The results showed that PRMT5 expression was not significantly different between healthy lean and obese humans, but exhibited a trend to decrease during the development of glucose intolerance." (PMID 33304767, 2020).
graft versus host disease (1 paper, 2024). An immune system disorder that occurs after allogeneic hematopoietic stem cell transplant and is a reaction of donor immune cells against host tissues. "In T cells, PRMT5 has been reported to induce IFN signaling in a graft-versus-host disease mouse model and T cell activation." (PMID 38838142, 2024).
hemoglobinopathies (1 paper, 2021). "Other epigenetic enzymatic activities implicated in γ-globin repression that have potential to serve as druggable targets in hemoglobinopathies include the EHMT1/2 histone methyltransferase heterodimer and the PRMT5 and PRMT1 protein arginine methyltransferases." (PMID 34713248, 2021). "Of note, a number of PRMT small molecule inhibitors specifically targeting PRMT5 and PRMT1 have been developed and are now entering clinical trials, but not yet for treating hemoglobinopathies." (PMID 34713248, 2021).
hepatoblastoma (1 paper, 2023). Hepatoblastoma (HB) is a malignant hepatic tumor and is the most common pediatric liver cancer. "After deriving cell lines from the mouse model, we map cancer dependency genes using CRISPR-Cas9 screening and identify druggable targets shared with human hepatoblastoma (e.g., CDK7, CDK9, PRMT1, PRMT5)." (PMID 37414763, 2023).
herpes simplex infection (1 paper, 2021). "KEGG pathway analysis results revealed that the top four most enriched pathways for PRMT4 and PRMT5 methylomes were spliceosome, mRNA surveillance pathway, RNA transport, and herpes simplex infection, which were similar to those for PRMT7 methylome." (PMID 33782401, 2021).
Hypercalcemia (1 paper, 2023). An abnormally increased calcium concentration in the blood. "Our findings suggested that these histone methylations may mediate, in part, the PRMT5 repression of 1,25(OH)2D3 induced Cyp24a1 transcription at times when protection against hypercalcemia is not needed." (PMID 37408241, 2023).
Insulin resistance (1 paper, 2020). Increased resistance towards insulin, that is, diminished effectiveness of insulin in reducing blood glucose levels. "Deletion of Prmt5 disrupts fatty acid metabolism and impairs lipid droplet biogenesis in white adipocytes, which causes age‐dependent fat loss and lipodystrophy, and eventually leads to insulin resistance and systemic metabolic syndrome." (PMID 33304767, 2020). "The insulin resistance and impaired energy expenditure phenotypes prompted us to examine whether lipid metabolism is affected by Prmt5 knockout." (PMID 33304767, 2020). "Mice lacking PRMT5 in adipocytes develop progressive lipodystrophy and insulin resistance, resembling BSCL2‐mutation disease." (PMID 33304767, 2020).
kidney damage (1 paper, 2019). "In conclusion, the present study verified that PRMT5 inhibition offers protection against kidney damage induced by I/R." (PMID 31885778, 2019).
lentivirus infection (1 paper, 2012). Virus diseases caused by the Lentivirus genus. "The shRNA dramatically reduced expression of PRMT5 protein in LNCaP cells 4 days after the lentivirus infection (lane 2) compared with that expression by a non-target (NT) shRNA (lane 1), whose sequence did not match any known human gene." (PMID 22952863, 2012).
limb ischemia (1 paper, 2022). A ischemia that involves the limb. "Furthermore, we found that endothelial-specific deletion of Prmt5 substantially attenuated limb ischemia–induced neovascularization and EC proliferation." (PMID 35531958, 2022).
liver fibrosis (1 paper, 2025). "At the same time, compared with the SIRT7-knockdown group, OA treatment in SIRT7-knockdown cells did not further suppress the expression of PRMT5 and liver fibrosis markers." (PMID 40777599, 2025).
malignant pleural mesothelioma (1 paper, 2021). A malignant neoplasm that arises from mesothelial cells in the pleura and shows a diffuse growth pattern. "We hypothesized that small molecule transcriptional perturbation could be harnessed to target a cellular dependency involving protein arginine methyltransferase 5 (PRMT5) in the context of methylthioadenosine phosphorylase (MTAP) deletion, seen frequently in malignant pleural mesothelioma (MPM)." (PMID 33795785, 2021).
Merkel cell carcinoma (1 paper, 2025). "Virus-positive Merkel cell carcinoma (MCC) serves as an ideal model to explore PRMT5’s role in alternative splicing regulation, as it is driven by the MYC paralog MYCL." (PMID 40846633, 2025). "In this study, we examined how PRMT5 regulates the Tip60-EP400 complex, which is recruited by MYCL in Merkel cell carcinoma." (PMID 40846633, 2025). "The study reveals that PRMT5-mediated methylation of SRSF1 preserves full-length Tip60, sustaining Tip60-EP400 complex–dependent chromatin repair and survival in Merkel cell carcinoma, highlighting a therapeutic vulnerability." (PMID 40846633, 2025).
metabolic syndrome (1 paper, 2023). A cluster of metabolic risk factors for CARDIOVASCULAR DISEASES and TYPE 2 DIABETES MELLITUS. "PRMT5 catalyzes Arg57 methylation of SHP to augments the SHP repression function and mitigates the risk of metabolic syndrome." (PMID 37143582, 2023). "PRMT5 catalyzes Arg57 methylation of SHP to augments the SHP repression function and reduce the occurrence of metabolic syndrome." (PMID 37143582, 2023).